FOXP3 (forkhead box P3)
Diseases named in the same sentence as FOXP3 in open-access papers (continued):
Sharing a sentence is not in itself a finding about the gene and the disease.
tumor (continued). "Foxp3+, CD8+ and CD3+ cell densities in biopsy samples from 106 patients were assessed by standard immunohistochemistry (IHC) and evaluated for their association with tumour regression grade and survival." (PMID 28177891, 2017). "Therefore, vaccine success can be theoretically determined by the changes in the ratio of the ICOS (anti-tumor effector activity) to FoxP3 (pro-tumor immunosuppressive activity) expression on CD4+ T-cells." (PMID 28304339, 2017). "VEGF-A production by FOXP3+ Treg cells also contributes to tumor angiogenesis in vivo." (PMID 29136509, 2017). "Foxp3+ regulatory T cells (Tregs) inhibit anti-tumour immunity and may limit any response to chemotherapy and radiotherapy." (PMID 28177891, 2017). "The reason may be, tumor cells primarily express self-antigens, and FoxP3+ T cells can efficiently suppress immune responses to self-antigens." (PMID 29450136, 2017). "Interestingly, there were significant increases in Foxp3 and IL10 expression, which are associated with immunosuppression in the tumor microenvironment." (PMID 28620375, 2017). "Tumor FOXP3 expression has a positive correlation with Treg cell counts in our NSCLC specimens." (PMID 28716029, 2017). "In addition to natural (n)Treg and induced (i)Treg cells that develop from naive precursors, suppressive IL-17A+Foxp3+ and ex-Th17 Foxp3+ cells are converted from IL-17A+Foxp3neg cells in tumour-bearing mice." (PMID 28290453, 2017). "Furthermore, the percentages of CD11b+ Gr-1+ (myeloid-derived suppressor cells, MDSCs) and CD25+ Foxp3+ (mainly expressed in regulatory T cells, Tregs) within the tumor tissues of DC-VEC group decreased mildly in DC-VEC group." (PMID 28978039, 2017). "Moreover, grafted D2F2 tumor cells grew faster and intratumoral Foxp3+ cell accumulation was observed in these mice compared to sham-treated controls." (PMID 28332605, 2017). "The CCL22-CCR4 axis could induce the expression of FoxP3 in Tregs and infiltrate FoxP3 + Treg selectively into tumor sites, contributing to form an immunocompromised environment in favor of tumor growth." (PMID 28086903, 2017). "To further evaluate the systemic immunosuppressive status of the 2cKO tumor bearing mice, we calculated the population of CD4+ Foxp3+ Tregs in spleen, lymph nodes and peripheral blood from wild type mice or 2cKO tumor bearing mice respectively by quantitative flow cytometric analysis." (PMID 28592285, 2017). "The 2nd treatment modality involved local injection of OX plus an IND-PL nanovesicle to induce the recruitment of cytotoxic CD8+ T lymphocytes, depletion of Tregs, reversal of the CD8+/Foxp3+ ratio, cytotoxic tumor killing, and tumor shrinkage at the local injection site." (PMID 29180759, 2017). "Accordingly, FOXP3 expression decreased the tumor size and weight in the xenograft model." (PMID 28591725, 2017). "The intensity of the infiltration of the tumor stroma by CD8+/FoxP3+ lymphocytes may constitute an independent prognostic factor in the group of CRS patients with stages IIA, IIIB, and IIIC, which requires confirmation in prospective studies." (PMID 28343267, 2017). "It is important to note that besides negative regulation of COX2, there might be also other targets mediating the tumor suppressor function of FOXP3-NFκB interaction." (PMID 28591725, 2017). "Ectopic expression of FOXP3 contributed to tumor growth and metastasis in NSCLC cells (A549 and H460) by promoting cell proliferation, migration and invasion as evidenced by cell viability assay, colony formation assay, soft agar assay, wound healing assay and transwell assay." (PMID 28716029, 2017). "IL-33 blockade dramatically reduced FoxP3 expression in NSCLC tumor tissues." (PMID 28978138, 2017). "These help in maintaining enhanced FOXP3 expression in tumor-CD8+ Treg." (PMID 28487507, 2017). "Thus, we analyzed the percentage of FoxP3+ cells in the CD4+ T cells from the spleens of the different treatment groups in non-tumor bearing mice." (PMID 28029653, 2017).
tumor (continued). "Interestingly, in stratified analyses by compartments within tumor FoxP3+ Tregs infiltrating into, FoxP3+ Tregs invading stromal compartment significantly improved 3 and 5-year OS, yet OS wasn’t improved when FoxP3+ Tregs infiltrated into intraepithelium only." (PMID 29088871, 2017). "In this review the role of the EGFR for the functioning of the immune system is discussed, alongside how EGFR antagonist treatment could be impacting tumor growth by blocking macrophage and FoxP3-expressing regulatory CD4+ T cell function." (PMID 28970798, 2017). "Interestingly, we observed a high expression of S1P1 only on tumor antigen-specific Treg in the BM, while S1P1 expression was low on CD25+ FoxP3+ Treg, CD25-FoxP3-Tcon, tumor specific Tcon in PB and BM, and tumor specific Treg in PB." (PMID 28224210, 2017). "However, its inactivation was recently shown to be required for the activation and tumor infiltration of Foxp3 Tregs in vivo." (PMID 28492364, 2017). "Furthermore, Nrp-1 acts as a key mediator of Foxp3+ Treg cell infiltration into the tumor site, resulting in a dampened anti-tumor immune response." (PMID 27075020, 2016). "Dense infiltration of FoxP3+ TILs in the infiltration zone was associated with impaired survival, whereas infiltration of FoxP3+ TILs in the tumor center did not alter survival." (PMID 27449756, 2016). "The increased levels of FoxP3+/−Helios+GARP+LAP+ Tregs in LICRC patients could be attributed to the advanced metastatic stage of these patients, and the associated tumour-mediated immunosuppression that could be expected." (PMID 26885615, 2016). "Our study provides at least a clue that FOXP3+ Tregs migration to tumours may be due to recruitment to CCL20." (PMID 27725696, 2016). "Moreover, FOXP3 overexpression in human cancer cell lines was shown to repress tumor growth and metastasis." (PMID 26735887, 2016). "The abundance of FoxP3+ Treg cells increased in wild-type tumours after radiation." (PMID 28008921, 2016). "While Th17s and Tregs have unique roles in the tumor microenvironment, interpretations of this ratio may be confounded by the presence of IL-17+FoxP3+ T cells, an intermediate Treg/Th17 phenotype that may be relevant to tumorigenesis." (PMID 27784305, 2016). "Critically, NK cytotoxicity was clearly inhibited by TGF‐β and the expression of activating receptor NKp46 was downregulated in neoplastic lymph nodes, suggesting that inactivated NK cells enhance tumor formation during BLV‐infection by inducing TGF‐β secretion from CD4+CD25+ Foxp3+ T cells." (PMID 27042304, 2016). "Different densities of Foxp3+TILs were found in the stroma surrounding the tumor cells." (PMID 27602763, 2016). "In comparison the majority of nuclei within the sarcoid tumour mass expressed FOXP3." (PMID 27160146, 2016). "Although it was first described as restricted to hematopoietic lineages, recent studies have shown FOXP3 expression in several tissues, including tumor cells, and it has also been suggested a nuclear or cytoplasmic localization, which can be related with patient prognosis." (PMID 27830498, 2016). "FOXP3 (forkhead transcription factor 3) was initially described as a marker for regulatory T cells; however, its expression in several types of tumor cells has already been described and may have prognostic significance." (PMID 27830498, 2016). "Indeed, in our model as well, we found that while PLX4720 alone appears to increase the infiltration of CD8+ T cells into the periphery of the tumor, unfortunately there was also a moderate increase in FoxP3 T regulatory cells." (PMID 26943572, 2016). "The majority of tumor-infiltrating FoxP3+ T cells were FoxP3hiCD45RA−CD4+ aTreg cells (Fr." (PMID 27177223, 2016). "Also, the presence of infiltrating CD4+, CD8+, and FOXP3+ cells in tumor samples was assessed by immunohistochemistry." (PMID 27463005, 2016).
tumor (continued). "Additionally, lower intensity TNFR2 expression was observed for tumor-infiltrating CD4+Foxp3− and CD8+ Teff cells, and for PBMC-derived Teff cells following in vitro stimulation with PHA-P/IL-2 or specific cognate antigenic peptide." (PMID 27626702, 2016). "However, the CKM cocktail tended to inhibit expression of CCL22, CXXL12, as well as FoxP3 in our in vivo tumor model." (PMID 26956047, 2016). "Close CD8+-FoxP3+ interactions may be favourable due to a down-regulated inflammatory environment, which can promote tumour growth." (PMID 27494875, 2016). "Moreover, the blockade of PD-L1 mitigated the effect of CD8+ T cells on the number of FoxP3 T regulatory cells in the tumor microenvironment." (PMID 26943572, 2016). "Similarly, we detected increased PD-1 expression on CD4+Foxp3- TILs isolated from α-CTLA-4-treated MB49 tumour-bearing mice." (PMID 27498556, 2016). "Our findings provided clues that FOXP3+ Tregs migration to tumours may be due to recruitment to CCL20." (PMID 27725696, 2016). "High tumour grade was shown to be significantly associated with tumour infiltration (intratumoural, stromal) by CD4+ and CD8+ T cells and stromal FOXP3+ T cells, which may have contributed to the NAC-induced pCR." (PMID 27777963, 2016). "Forkhead box protein P3+ (FoxP3+) T cells suppress tumor immunity." (PMID 27120805, 2016). "Foxp3 regulates tumor progression by expressing not only in Tregs, but also in tumor cells of HCC, and it may also be functional in tumor cells of HCC." (PMID 29201748, 2016). "For example, mAbs targeting CCR4, a chemokine receptor heavily involved in Treg recruitment to the TME, have shown promising results in clinical and laboratory studies, effectively depleting activated FoxP3+CCR4+ Tregs with only a limited impact on tumor-infiltrating Teff and CTL subsets." (PMID 27509527, 2016). "Naringenin administration reduced Foxp3 expression in the lungs of tumor-bearing mice." (PMID 27036297, 2016). "After NAC, however, there was a significantly higher % of blood FOXP3+ T cells and significantly higher levels of intratumoural (tumour cell nests) FOXP3+ T cells in those women whose tumours had a poor pathological response to 8 cycles of NAC (p = 0.001 and p = 0.016, resp)." (PMID 27777963, 2016). "Next, we assessed tumor-derived Nrp-1-specific Foxp3+ Treg cell phenotypes during tumorigenesis." (PMID 27075020, 2016). "The increase in FoxP3+ Tregs in the Axl knockout tumours suggests an adaptive immune resistance mechanism after radiation that is greater in the less responsive Axl Cr#1 tumours compared with the pooled Axl CRISPR tumours." (PMID 28008921, 2016). "It has been previously shown that human gastric MALT lymphoma biopsies are infiltrated by large numbers of Foxp3+ Tregs, which can exhibit a suppressive behaviour toward effector T cells and may be essential for optimal tumor B-cell proliferation." (PMID 26657504, 2016). "The authors speculated that FoxP3+ T-regulatory cells might lose their ability to suppress antitumor immunity when they are found within the tumor tissue." (PMID 27449756, 2016). "High tumor infiltration of Foxp3+ Tregs is supposed to be correlated with the poor outcomes." (PMID 27153545, 2016). "In the absence of further clinical and functional data, we cannot comment on the exact nature and origin of FoxP3+/–Helios+GARP+LAP+ Tregs whether thymic or peripheral or even induced in the tumour microenvironment." (PMID 26885615, 2016). "This may be due to BPA producing its cancer-promoting effects through the STAT3 pathway, which upregulates Foxp3+ Treg cells and downregulates the Th1 inflammatory response in the tumor microenvironment." (PMID 29051427, 2016). "The decreased number of FoxP3+ Tregs in the tumor cell area might explain the increased numbers of TFH cells, as Tregs control the number of TFH cells." (PMID 27999289, 2016).
tumor (continued). "We could show that tumor infiltrating CD8+ and FoxP3 positive cells were associated with disease free survival after pulmonary metastasectomy and OS." (PMID 27449756, 2016). "It was found that CTLA-4 blockade therapy could greatly reduce the percentages of Tregs (CD3+CD4+Foxp3+) in secondary tumours." (PMID 27767031, 2016). "We observed almost identical results when measuring tumor-derived CD4+Foxp3+ T cells." (PMID 27075020, 2016). "Moreover the nuclei of many basal cells as well as cells in the stratum spinosum of the epidermis overlying the tumour also stained positive for FOXP3." (PMID 27160146, 2016). "The reduction in the tumour was at least 10-fold for FOXP3+ and 4-fold for CTLA-4+." (PMID 27777963, 2016). "However, the number of spleen-derived TGF-β+CD4+Foxp3+ T cells increased compared with WT, with the exception of the tumor and spleen." (PMID 27075020, 2016). "As the tumour resection was performed 8 weeks after RCT, we hypothesized that the decrease of FoxP3+ inflammatory cells was rather a change of the tumour microenvironment induced by RCT than a direct cytotoxic effect of the therapy." (PMID 27494875, 2016). "The observation that CD39 and CTLA-4 are co-expressed in the majority of intratumoral Treg suggests that these two molecules may be key regulators of functional FoxP3+ Tregs in the tumor." (PMID 27195113, 2016). "This interaction could thereby trigger CD200R-mediated Foxp3 expression, resulting in Foxp3-positive, type 2-differentiated macrophages with immunosuppressive effects in different tumour microenvironments." (PMID 27731341, 2016). "Further studies of the ratio of FoxP3+ Tregs to different tumor infiltrating lymphocytes (CD8, CD3) could add insight into the immunologic microenvironment associated with immune evasion." (PMID 26462617, 2015). "Although we observed a highly significant difference in proportions of Foxp3− and Foxp3+ T cells expressing CCR4 in spleens and lymph nodes, this difference was considerably reduced in the tumour where CCR4 was expressed on a high proportion of both Foxp3− and Foxp3+ T cells." (PMID 25495686, 2015). "Notably, only a few of the selected studies focused on the prognostic role of FOXP3 expression distribution in tumor cells." (PMID 26305693, 2015). "However, the pixel count for tumor-infiltrating Tbet+ cells was generally (p < 0.0005; Mann–Whitney) but also in each sample (p = 0.011; paired sample t test) higher than that of Foxp3+ cells." (PMID 26357849, 2015). "Ex vivo studies of NHL patient samples revealed that direct cell contact with tumor cells induced differentiation of autologous PBMCs into CD4+CD25+FoxP3+ Tregs that were found to be directly responsible for effector T cell hyporesponsiveness by in vitro depletion experiments." (PMID 25941795, 2015). "In addition, regulatory T cells defined as forkhead box protein 3 (FOXP3)+ T cells play a pivotal role in suppressing anti-tumor immunity." (PMID 26341640, 2015). "In particular, degradation of FOXP3 may be the desired goal in tumor biology, to allow the propagation of antitumor responses, as has been demonstrated with anti-CTLA4 therapies." (PMID 26561546, 2015). "The finding that a high density of infiltrating FoxP3+ Tregs was associated with unfavorable outcome in a wide range of tumors supported the theory that the tumor-infiltrating FoxP3+ Tregs could be an escape mechanism of human cancers to the immune response." (PMID 26462617, 2015). "Moreover, in many cancers, the prognostic effect of FoxP3+ Treg is highly correlated with tumor stage or molecular subtype." (PMID 26462617, 2015). "In addition, all CD4+ T cell subsets markedly increased in tumor draining lymph nodes at the late stage of 4T1 tumor progression, whereas in E0771-bearing mice, only CD4+IL17+ and CD4+Foxp3+ subsets had significant increases in tumor draining lymph nodes." (PMID 25968569, 2015).
tumor (continued). "We hypothesized that in ER+ subgroup patients, the predominant subpopulations of FOXP3+ T cells was hormonal dependent, and may possess anti-tumor activity." (PMID 26305693, 2015). "Higher levels of tumor PD-L1, were associated with low relative ratios of CD8+ to Foxp3+ T-cells." (PMID 26317902, 2015). "Interestingly, AMPK deficiency seemed to have minimal influence on the expression of Foxp3, IL-17 and IL-4 in the tumor microenvironment." (PMID 25760243, 2015). "In addition, tumor-infiltrating forkhead box P3 (Foxp3)+ cells were examined using immunohistochemistry." (PMID 25352158, 2015). "The prognostic correlations of FOXP3+ TILs could be affected by tumor microenvironment, including tumor location, histological and molecular subtypes, as well as different types of immune response." (PMID 26475790, 2015). "Interestingly, CTLA-4 levels and the percentages of tumor infiltrating CD4+Foxp3+ Tregs remained unchanged." (PMID 25851535, 2015). "Furthermore, the ratio of CD8+ to Foxp3+ T-cells, reflecting a balance between tumor-reactive and immunosuppressive TIL subpopulations, was also found to be higher in primary disease." (PMID 26317902, 2015). "CD4+CD25+Foxp3+ natural regulatory T (Treg) cells might play critical role(s) in the suppression of anti-tumor immune response and thus shed light on tumor progression from benign to malignant." (PMID 26020249, 2015). "Finally, Kaplan-Meier analysis revealed that the relative abundance of FOXP3-expressing CD3+CD56+ cells in tumor tissues was significantly correlated with the survival of HCC patients." (PMID 26437631, 2015). "FOXP3 was expressed in intratumoral lymphocytes, peritumoral lymphocytes, and/or tumor cells." (PMID 26305693, 2015). "Based on the potent immunoregulatory function these cells have on immune responses and inflammation, it is reasonable to conceive that Foxp3+CD4+ T cells may in fact help prevent or delay inflammation-mediated tumor development." (PMID 26604855, 2015). "Therefore, it is necessary and still difficult to elucidate the mechanism of Foxp3 translocation in tumor cells." (PMID 25779374, 2015). "The discrepant prognostic effect of FoxP3+ Tregs could arise from different biologic properties of specific tumor types, and the positive impact may be related to their anti-inflammatory effects in several tumors." (PMID 26462617, 2015). "As PD-L1 expression is known to increase the amount of FOXP3-positive lymphocytes we analyzed whether there is a correlation between PD-L1 expression by tumor cells and the amount of FOXP3-positive lymphocytes." (PMID 26517811, 2015). "One of the most studied immune-suppressive cell types associated with tumor progression is regulatory T cells (Treg), characterized by their expression of CD4, high CD25 (CD4+CD25+CD127low/neg) as well as the transcription factor forkhead box P3 (FoxP3)." (PMID 26648934, 2015). "As a result, the positive impact of FoxP3+ Tregs may be partially attribute to down regulate an unresolved inflammatory response which could promote tumor progression." (PMID 26462617, 2015). "The number of Foxp3+ cells in the tumor samples increased from stage I to stage IV." (PMID 25352158, 2015). "This might occur via switching of tumor infiltrating CD4+ T cells to Foxp3+ Tregs by the high TGF-β level present in the immunosuppressive environment of the tumor." (PMID 26109431, 2015). "Countering the HATs, the HDACs deacetylate FOXP3, which reduces Treg development and immunosuppressive function, and also provides a therapeutic target for enhancing immunosuppressive (and potentially anti-tumor) activity in patients." (PMID 26124919, 2015). "Nevertheless, the analysis of Treg in several tumor types indicated that FoxP3+ expression may be related to CD4+ T-cell activation rather than to an immune suppressive phenotype." (PMID 26161395, 2015).